PML (PML nuclear body scaffold)
Diseases named in the same sentence as PML in open-access papers (continued):
Sharing a sentence is not in itself a finding about the gene and the disease.
infection (continued). "This activity of IE1 correlates with the functional activities of IE1 during infection and the antiviral role of PML in HCMV replication is well established using PML-overexpressing and knockdown cells." (PMID 25812002, 2015). "Here again, PML SUMOylation influences the course of infection as ICP0 favors interaction with and degradation of certain SUMOylated forms of PML." (PMID 25513827, 2014). "Soon after infection, EMCV induces the transfer of PML from the nucleoplasm to the nuclear matrix, both in IFN-treated and PMLIII-expressing cells." (PMID 23734343, 2013). "For example, in the context of antiviral defense, during varicella-zoster virus (VZV) or encephalomyocarditis virus (EMCV) infection, only PMLIV sequesters viral proteins in PML NBs and inhibits viral production." (PMID 23734343, 2013). "L2 and the viral genome co-localize in the nucleus at PML nuclear bodies (PML NB; also called ND10 domains) following infection." (PMID 21994730, 2011). "Following infection, key components of the DDR, like ATM, RPA, ATRIP, 53BP1, γ-H2AX are recruited into viral replication centers, with PML NBs juxtaposed to these." (PMID 21998700, 2011). "Upon the early stages of infection right after cell entry, HSV-1 and HCMV utilize viral proteins that effectively disrupt the structure and disable the function of the PML-NBs in restricting viral gene expression and replication." (PMID 22102817, 2011). "In agreement with infection data, these results imply that ICP0 exhibits substrate selectivity with regard to SUMO-conjugated species, in that PML is targeted more efficiently than SUMO conjugates in general." (PMID 21949651, 2011). "Here, we demonstrate that EBV BNRF1 is a novel PML-NB-interacting viral protein, and that this interaction is important for supporting EBV primary infection." (PMID 22102817, 2011). "During infections with HHV-1, new PML-NBs are generated at the sites where infecting viral genomes enter the nucleus." (PMID 20838604, 2010). "In summary, these data clearly identified the ND10 proteins PML, hDaxx and ATRX as cellular restriction factors responsible for silencing of HCMV IE gene expression directly upon infection." (PMID 21994592, 2009). "Cells over-expressing nuclear PML I showed a typical pattern of localization that agrees with earlier reports: by 2h post infection, both ICP0 and nuclear PML co-localized at ND10." (PMID 18509536, 2008). "During infection with porcine reproductive and respiratory syndrome virus (PRRSV), the scaffold protein TRIM19 promotes the formation of PML-NBs in reliance of its α-helical CC domain, which drives the homomeric or heteromeric assembly of TRIM proteins, directly contributing to antiviral activity." (PMID 41001050, 2025). "During infections with HSV-1 strains lacking ICP0 ubiquitin ligase functions, PML and PML bodies have been shown to contribute to interferon stimulatory activities that restrict the infection." (PMID 40577456, 2025). "We conclude that PML entrapment of HSV-1 genomes not to sterically inhibit the stable deposition of histones H2A or H2B at vDNA upon nuclear infection." (PMID 40834051, 2025). "Indeed, IE72 indirectly influences PML stability, since IE72-Daxx interaction drives LUNA transcription during lytic infection." (PMID 41373712, 2025). "We demonstrate PML to be an accessory component of viral chromatin prior to its degradation by ICP0, confirming ICP0 capable of targeting multiple anti-viral host factors bound to vDNA for proteasomal degradation to stimulate the progress of infection." (PMID 39185184, 2024). "Moreover, EBNA1 promotes the phosphorylation and degradation of promyelocytic leukemia (PML) proteins in the nuclear bodies (NBs) by casein kinase 2 (CK2) and ubiquitin-specific protease 7 (USP7), respectively, leading to lytic infection." (PMID 39772271, 2024).
infection (continued). "Nor do we discount a role for PML-NBs in the establishment or maintenance of nucleosomal heterochromatin during other phases of infection (e.g., HSV-1 latency)." (PMID 39185184, 2024). "We conclude that PML entrapment of HSV-1 genomes not to sterically inhibit the deposition of histones H2A or H2B at vDNA upon nuclear infection." (PMID 39185184, 2024). "Upon infection of non-neuronal cells, HSV-1 genomes rapidly associate with PML-NBs and there is evidence for silencing through H3K9me2/me3 at these bodies." (PMID 38076966, 2023). "Additional findings from a variety of groups have since shown that PML-NBs also bind to and repress the genomes of several different viruses, including HCMV, suggesting sequestration by PML-NBs is an initial roadblock to infection that must be overcome." (PMID 37439556, 2023). "Furthermore, in our studies of HBV-ΔX infection of HepG2-NTCP cells with inducible HBx expression, preformed cccDNA can be recognized and directed to PML bodies in the presence of SMC5/6 and SLF2." (PMID 37338350, 2023). "Paradoxically, HSV-1 virus yield was substantially reduced in the absence of PML proteins in Hep2 cells at low-dose infections, suggesting a supportive role of PML-NB components for efficient virus replication." (PMID 38140525, 2023). "Though only a small portion of HBV core is SUMOylated, this particular fraction localizes in the nonsoluble nuclear matrix fraction, indicating that it is recruited into specific, but not all, PML-NBs during infection." (PMID 37199632, 2023). "Expression and steady-state levels of all analyzed cellular proteins (β-actin, USP7, Daxx, Rad50, Nbs1, Mre11, and PML) were not altered in UBM2 H5pm4250 versus WT H5pg4100 infection." (PMID 35254132, 2022). "Since expression of several PML-NB proteins, including Sp100 and PML itself, can be upregulated by IFN treatment, we hypothesized that PML cages may arise due to IFN-mediated increase of PML-NB protein levels during infection with IE1-deleted virus." (PMID 35319461, 2022). "In H1299 cells, protein levels of PML isoforms were not significantly changed during HAdV-wt infection." (PMID 35699431, 2022). "Furthermore, we found that PML expression was up-regulated by both MDV strains prior to 14 dpi, and MDV/RB1B infection showed a higher efficiency than that of MDV/CVI988 infection." (PMID 36680047, 2022). "In subsequent immunofluorescence analysis we observed that PML, which usually shows a diffuse, nuclear distribution in HCMV-infected cells, localizes to unusually large, ring-like structures after infection with recombinant cytomegaloviruses." (PMID 35319461, 2022). "Similar capsid accumulations were detected in non-transduced HFF after infection with IE1-deficient viruses based on strain TB40E or AD169, suggesting a virus strain-independent entrapment by endogenous PML." (PMID 35319461, 2022). "Taken together, these data suggest that PML-NBs are not disrupted by IE1 upon cross species infection and point to a contribution of the PML-based intrinsic defense to the species barrier." (PMID 34370791, 2021). "Pin1 interaction with PML-IV and subsequent colocalization in PML NBs resulted in sustained IRF3 activation and higher IFN-β induction upon poly I:C treatment or infection with a variety of DNA or RNA viruses including Sendai virus, EMCV, human T-cell lymphotrophic virus 1, IAV or vaccinia virus." (PMID 33807177, 2021). "This correlates with a comparative functional analysis of human and rat cytomegalovirus IE1 showing that neutralization of PML-NBs occurs only in cells of the natural host species but not during cross-species infection." (PMID 34370791, 2021). "Agreeably, knocking down expression of individual PML NB components such as PML, Daxx, and Sp100 in primary human fibroblasts showed a de-repressing effect on HCMV IE gene expression at low multiplicity of infection." (PMID 34513832, 2021).
infection (continued). "This is in accordance with previously published results on MCMV demonstrating that knocking-down of PML-NB components significantly increases viral protein production in cross-species infection experiments, however, does not result in productive infection." (PMID 34370791, 2021). "Particularly, upon infection, PML proteins are hyper-SUMOylated and degraded with concomitant active viral expression; on the contrary, upon antioxidant treatment or iron chelation, HIV-1 reestablishes a latent phenotype and PML levels are restored." (PMID 33760045, 2021). "To dismiss the fact that less integration in PML KO cells might result from the skewing of infection toward a lytic cycle, we measured the HHV-6B DNA copy numbers in PML KO relative to WT cells." (PMID 32658923, 2020). "We found that bacteria were no longer detectable and that skin infiltrating PML, Ly6C expression and tissue edema were back to base line 2 weeks after infection." (PMID 32639232, 2020). "In order to establish the role of Myd88 in the innate memory model, we infected Myd88-/- mice for 3 weeks and analyzed transcriptional priming (without secondary infection), as well as killing capacity and PML recruitment 5 days after re-challenge." (PMID 32639232, 2020). "The SV40 large T antigen (TAg) localizes to PML NBs during infection, or when ectopically expressed, and the expression of TAg alone is sufficient to localize reporter constructs containing the SV40 origin of replication to PML NBs." (PMID 32013091, 2020). "Skin colonization with S. aureus led to a 50% increase in the frequency of Ly6Chi Mφ after infection of sDMDMm2 mice while it did not affect the abundance of infection-induced PML." (PMID 32639232, 2020). "In the absence of E2A SUMOylation, there are fewer E2A/PML (bottom) and E2A/Sp100A (bottom) interactions and increases in Sp100A levels are lower than in wt infection (bottom)." (PMID 32184235, 2020). "In summary, Sp100 levels are reduced by VZV ORF61p from the onset of infection but since VZV does not completely disrupt PML-NBs, IFN-response can rise Sp100 protein levels, which are kept dispersed in the nucleoplasm by ORF61p." (PMID 33598438, 2020). "As PML tracks represent sites of active viral transcription, it is not surprising that infection with the E2A SCM mutant virus resulted in a reduced replication efficacy." (PMID 32184235, 2020). "Under productive infection conditions, HIRA recruitment to infecting viral genomes could only be observed following the saturation of PML-NB host defences and the onset of ΔICP0 HSV-1 DNA replication by 6 hpi." (PMID 30901352, 2019). "In contrast to PML, which is a well-characterized substrate of ICP0, western blot analysis of infected whole cell lysates revealed that HIRA protein levels remained stable throughout infection." (PMID 30901352, 2019). "Our investigation was prompted by the observation that infection of primary endothelial cells with KSHV does not result in the disruption of PML NBs, in contrast to infection with HCMV and to what has been noted for many other herpesviruses." (PMID 31059555, 2019). "We conclude that HIRA does not stably colocalize with input vDNA or PML-NBs under infection conditions in which key intrinsic PML-NB restriction factors (PML, Sp100, Daxx, and ATRX;) rapidly entrap and silence vDNA following its nuclear entry." (PMID 30901352, 2019). "Notably, exogenous cytokine stimulation (IFN-β and IFN-γ) can induce HIRA localization to PML-NBs independently of infection, supporting a role for HIRA at PML-NBs as a component of the innate immune response." (PMID 30901352, 2019). "The entrapment of incoming wild type HSV-1 genomes by PML NBs is not a unique feature of latency, because it has recently been shown to occur prior to the onset of lytic infection, as part of the intrinsic antiviral response." (PMID 30235352, 2018).
infection (continued). "The viral Z-transactivator regulatory protein Zta, which is critical for productive lytic infection, was identified for being necessary and sufficient for the disruption of PML-NBs; however it does not mediate degradation of PML." (PMID 29065450, 2017). "The case of PML, whose de-SUMOylation counteracts bacterial infection, illustrates how SUMO alterations of some host proteins can also constitute danger signals for the cells, leading to a response aimed to limit infection." (PMID 28074026, 2017). "Strikingly, we observed that PML does not control infection by Salmonella Typhimurium, even though this pathogen was also shown to induce a decrease in the Ubc9 level." (PMID 28074026, 2017). "In the absence of IFN-β, we found that the PML knockout (PML-KO) cells were slightly more permissive to infection by HIV-1NL-GFP than the control cells (<2-fold)." (PMID 28656178, 2017). "We found that MEF cells were up to 30 times more permissive to infection by the HIV-1 vector in the absence of PML." (PMID 27000403, 2016). "During infection with ICP0-null mutant HSV-1, PIAS1 also relocalized to the nuclear edge that contained infecting viral genomes, which was identified by the localization of PML or Daxx and the HSV-1 DNA-binding protein ICP4 (ΔICP0)." (PMID 27099310, 2016). "The differential colocalization of PIAS4 with PML in cells that have been infected or not indicates that PIAS4 localization is differentially regulated during infection." (PMID 26937035, 2016). "Because ICP0 is directly involved in the destabilization of PML-NBs in infected non-neuronal cells, we performed infections with a deletion virus unable to express ICP0." (PMID 27618691, 2016). "Models for the mechanisms by which ICP0 disrupts silencing in epithelial cells during lytic infection include degradation of cellular IFI16, degradation of PML and disruption of PML bodies, and disruption of the repressive HDAC-CoREST-LSD1-REST complex by dissociating HDAC." (PMID 27190217, 2016). "In this case again however since NPDs and PML can be observed together after infection with the ICP0 mutant, this proposal would require that NPD formation was linked to but not sufficient for PML disruption." (PMID 27706239, 2016). "Indeed, by immunofluorescence microscopy, we observed colocalization of PML with both full-length IFI16 and its PY domain at early stages of infection." (PMID 27935834, 2016). "Since PML interacted with STAT1, STAT2, HDAC1, and HDAC2, we investigated whether IE1 simultaneously interacts with PML, STAT1, STAT2, and HDACs during infection." (PMID 25812002, 2015). "Cytoplasmic IE62 was extensive in neurons with markers of late infection, including plasma membrane dissolution and fusion of neurons and their encapsulating SGC (white arrow), and the presence of large PML nuclear bodies that sequester VZV nucleocapsids and inhibit viral replication (yellow arrow)." (PMID 26090802, 2015). "Upon infection with HIV reporter virus, we found that the overexpression of the different isoforms reduced infectivity by approximately 1.5- to 3-fold in HFFs, suggesting that the overexpression of PML also has a moderate inhibitory effect on HIV infections." (PMID 26703718, 2015). "We did not observe a significant change in overall PML protein levels or significant changes in PML isoform distribution during infection with either the non-invasive (BS176) or wild-type (M90T) Shigella strains." (PMID 25848798, 2015). "This experiment revealed significantly more IE2-EYFP positive cells in the absence of PML, hDaxx and Sp100 compared to control cells siC upon infection at an MOI of 0.01 and 0.05." (PMID 26057166, 2015). "Staining of the apoptotic marker Annexin V confirmed the occurrence of massive apoptosis in GSCs two days after infection of shPML viruses, suggesting that increased GSC cell death may be a result of apoptosis induced by PML disruption." (PMID 26510911, 2015).
infection (continued). "Although we cannot exclude that PML acts on all three of these very diverse promoters, our results suggest that the transcription of the reporter gene is not affected by PML in our single cycle infection assays." (PMID 26703718, 2015). "The inhibitory effect of PML on HIV infectivity did not change over a wide range of multiplicity of infections (MOIs), suggesting that the antiviral effect of PML is not saturable by high viral loads." (PMID 26703718, 2015). "This shows that PML dispersal as observed during infection with herpes simplex virus type I and HCMV is not a prerequisite to antagonize the repressive effects of this cellular multiprotein complex on viral gene expression." (PMID 25412268, 2014). "Knock-down experiments in primary human cells show that KSHV-infection is restricted by the ND10 components PML and Sp100, but not by ATRX." (PMID 24453968, 2014). "This conclusion is based on the fact that foci of the episome-binding LANA-protein do not co-localize with PML or Sp100 speckles during the first 24 to 72 hours of a de novo infection." (PMID 25033267, 2014). "A role of PML in viral resistance in vivo is indicated by the increased sensitivity of PML knockout mice (as compared to the wild-type mice) to lymphocytic choriomeningitis virus (LCMV) and to vesicular stomatitis virus (VSV) infections." (PMID 23734343, 2013). "Early in infection, unknown SUMO conjugates, along with PML, are recruited to viral genomes that can be visualized as punctate foci in the nucleus." (PMID 23795346, 2012). "During infection, ICP0 localizes to promyelocytic leukemia (PML) nuclear bodies (PML-NBs, also known as ND10 or PODs) where it induces the proteasome-dependent degradation of PML, its small ubiquitin-like modifier (SUMO)-modified isoforms, and SUMO-modified Sp100." (PMID 21949651, 2011). "The similarity in PML disruption by EBNA3B and EBNA3C suggests that they might act either redundantly or cooperatively in this role during latency III infection." (PMID 18617993, 2008). "However, following latent infection of CD34+ pluripotent stem cells (HPCs), pp71 is retained in the cytoplasm and thus fails to disrupt PML-NB-induced defenses, suggesting cell type and/or infection stage specificity." (PMID 41373712, 2025). "However, infection upon knockdown of either PML or Daxx failed to abrogate the effects of MG132-mediated proteasome inhibition of synthesis suggesting the existence of other targets." (PMID 39655950, 2025). "However, following latent infection of CD34+ HPCs, pp71 is retained in the cytoplasm and thus fails to disrupt PML-NB-driven defenses, which suggests cell type and/or infection phase specificity." (PMID 37439556, 2023). "Thus, although SV40 replicates its genomic DNA close to PML NBs, no alterations or modifications of the NBs during infection have been detected." (PMID 37127643, 2023). "PML-NBs were slightly enlarged at 8 hr post-infection (hpi), when compared to non-infected cells." (PMID 35319461, 2022). "Interestingly, input genomes were still detectable at 72 hr after low MOI infection and were exclusively found inside large PML structures, independent of the number of genomes per nucleus." (PMID 35319461, 2022). "Since MCP was enriched in PML cages during HCMV∆IE1 infection, we applied correlative light and electron microscopy (CLEM) to investigate whether viral capsid proteins or whole nucleocapsids are sequestered by PML." (PMID 35319461, 2022). "Interestingly, primary fibroblasts derived from PML knockout mice are more vulnerable to infection with EMCV, suggesting that the PML protein might act as a restriction factor for EMCV replication." (PMID 34513832, 2021). "In addition, VRC formation and infectious virion production are not attenuated when PML negative mouse embryonic fibroblasts or mice are infected with murine polyomavirus (MPyV), suggesting that productive infection is not dependent on PML NBs." (PMID 32013091, 2020).